ACE (angiotensin I converting enzyme)
Diseases named in the same sentence as ACE in open-access papers (continued):
Sharing a sentence is not in itself a finding about the gene and the disease.
Hypertension (continued). "The human PT expresses ACE at the apical surface of RPTEC in order to convert angiotensin I to angiotensin II, which then plays a critical role in regulating sodium transport to influence hypertension through feedback onto the renal microvasculature and glomerulus." (PMID 28337147, 2017). "Studies comparing thiazides with ACE inhibitors in the treatment of hypertension for older patients could not be identified." (PMID 29047359, 2017). "In addition, among patients with diabetes, important comorbidities such as hypertension, heart failure (NYHA class I-II), and chronic kidney disease were more prevalent, and the rate of using antiplatelet therapy, ARBs, ACE inhibitors and beta blockers were higher." (PMID 28835613, 2017). "Approximately 80% of these adults have diagnosed hypertension (whether treated or untreated), while approximately 63% of T2DM adults have medication claims for ACE inhibitors/ARBs and 47% have medication claims for diuretics or other anti-hypertensive medications." (PMID 27895533, 2016). "Most studies have not found a relationship between ACE genotype and essential hypertension." (PMID 27871254, 2016). "Regardless of the history of hypertension, diabetes, angiotensin II receptor blockers (ARBs), or angiotensin-converting enzyme (ACE) inhibitor drugs, the mean level of creatinine was declined in the intervention group than control group, though the difference was not significant." (PMID 26693496, 2015). "The aim of our study was to characterize the association of clinical and genetic risk factors such as: ACE genotype (rs17997552, rs1800764, rs4459609) and RGS2 (rs2746071) with the development of hypertension (HT) and non-dipping phenomenon in patients with type 1 diabetes mellitus (T1DM)." (PMID 24562335, 2014). "The simultaneous inhibition of renin and ACE activities could provide a new alternative way to treat hypertension efficiently without severe negative side effects." (PMID 24603692, 2014). "Furthermore, ACE inhibitors or angiotensin-receptor-blocking agents should be used even in the absence of hypertension when a patient has vesicoureteral reflux and proteinuria." (PMID 23509659, 2012). "Also angiotensin-converting enzyme- (ACE-) inhibitors and calcium entry blockers, two groups of pharmaceuticals that are used primarily in treatment of hypertension, might influence DC function." (PMID 21976788, 2011). "Four hundred and forty-nine men and women 18 years of age or older with hypertension not controlled by an ACE inhibitor, a diuretic or any other monotherapy or anti-hypertensive combination not containing a diuretic in a fixed dose were considered eligible for inclusion in this eight-week study." (PMID 21556450, 2011). "Since ACE2 and ACE are coexpressed in many tissues, and ACE2 expression is both cardio- and renoprotective, acting in a counterregulatory manner to ACE in both experimental animals and humans, alterations in their activities and the ACE/ACE2 ratio may participate in hypertension and renal disease." (PMID 22110472, 2011). "The present doses may not have been sufficient to antagonise the severe hypertension of dTGRs caused by an over-expressed RAS, although ACE inhibition has been shown in SHRs in vitro and in vivo." (PMID 20721338, 2010). "ACE inhibitory activity of the pure peptides was confirmed in vitro, but the effect could not been seen in vivo despite prevention of hypertension." (PMID 20721338, 2010). "Lisinopril, an ACE inhibitor, did not suppress the development of hypertension." (PMID 27713243, 2010). "There are several candidate genes (ACE, angiotensinogen andaldosterone synthetase) in the RAAS that may potentially increase production ofeither angiotensin II or aldosterone, with suppression of renin, sodium retentionand hypertension." (PMID 17940670, 2007).
Hypertension (continued). "Although the presence of heart failure at study entry was not routinely recorded, ACE inhibitors were chiefly used for heart failure or hypertension during the recruitment period (1994–7), which predated evidence from the HOPE trial of benefit in other circumstances." (PMID 15771782, 2005). "Additionally, the absence of hypertension may indicate a decreased pathophysiological reliance on the renin-angiotensin system, which could explain the potential lower effectiveness of ACE inhibitors in normotensive SRC." (PMID 40084306, 2025). "Finally, angiotensin-converting enzyme (ACE) inhibitors were considered to address his proteinuria but were ultimately reserved until the KDIGO 2024 CKD guidelines were met: moderate-to-severe albuminuria, urine albumin-to-creatinine ratio (ACR) > 30 mg/mmol, or hypertension." (PMID 40890712, 2025). "Furthermore, commonly prescribed medications for hypertension, CVD, and depression—such as ACE inhibitors, statins, and selective serotonin reuptake inhibitors (SSRIs)—may alter systemic inflammatory and metabolic states, further attenuating the direct impact of RAR." (PMID 40568468, 2025). "Conversely, Zhang and coworkers reported that ACE inhibitors may compromise the effects of anti-angiogenic drugs in HCC mouse models, thus supporting the necessity for a rigorous monitoring and control of hypertension in MASLD-HCC patients to optimize treatment efficacy and outcomes." (PMID 38846491, 2024). "Hence, despite the interaction between garlic and ACE inhibitors, the patient’s hypertension may not have fatal effects when taken concurrently." (PMID 36771707, 2023). "In fact, the contribution of the altered angiotensinogen gene, ACE gene, or AT1 receptor gene was previously ruled out in a study that analyzed 2.4 million single nucleotide polymorphisms (SNPs) in approximately 300,000 patients with essential hypertension worldwide." (PMID 35163158, 2022). "Thus, our present study provides the first evidence that ACE inhibitor plus ARB dual therapy and either agent alone at equivalent antihypertensive doses are similarly effective in the primary prevention of microalbuminuria in patients with type 2 diabetes and hypertension." (PMID 34260595, 2021). "Moreover, in the 2012 Kidney Disease: Improving Global Outcomes (KDIGO) guideline, ACE inhibitors are stated as the commonly recommended antihypertensive drugs in comorbid hypertension and renal impairment; ARBs are recommended when ACE inhibitors are not tolerated or contraindicated." (PMID 34257706, 2021). "Finally, a retrospective, multi-center study demonstrated a lower risk of COVID-19 mortality in inhospital patients with hypertension and hospitalized due to COVID-19 who received ACE inhibitor/ARB compared to those who did not receive an ACE inhibitor/ARB (adjusted HR, 0.37; 95% CI, 0.15 to 0.89)." (PMID 32850989, 2020). "This suggests that the postponed development of high blood pressure in PC-H fed rats could be regulated through the renin-angiotensin system; however, since ACE and renin activities are measured in vitro these may not be directly transferable to effects in the rats." (PMID 30469459, 2018). "On hypertension medications, none of the participants were on both angiotensin-converting-enzyme (ACE) inhibitor and angiotensin receptor blocker while two participants were on ACE inhibitor and beta blocker, and four participants were on ACE inhibitor and calcium channel blocker." (PMID 28771472, 2017). "The United Kingdom Prospective Diabetes Study (UKPDS) studied >1000 patients and found a decrease in DR progression with an ACE inhibitor and a β1-adrenergic receptor antagonist, suggesting that the effect may due to mitigated hypertension rather than an ACE inhibitor-specific effect." (PMID 27618014, 2016).
Hypertension (continued). "Interestingly, this was the only hypertension medication that is correlated with higher IL-6 levels, and neither angiotensin-converting-enzyme (ACE)-inhibitors (ATC: C09AA), selective β-blocker agents (ATC: C07AB) nor a combination of these mediate this effect." (PMID 25147954, 2014). "National Institute for Health and Clinical Excellence in England recommends ACE inhibitors/ARBs in patients with diabetes mellitus irrespective of whether they have hypertension or not, if albumin:creatinine ratio is > 2.5 mg/mmol (men) or > 3.5 mg/mmol (women)." (PMID 24955116, 2014). "Interestingly, antihypertensive types that have shown consistent benefits in the treatment of hypertension in the very elderly (e.g. ACE-i and diuretics, as in the HYVET trial) were not linked with any of our adverse outcomes (i.e. MOH-3, OI, history of faints)." (PMID 23855394, 2013). "However we can speculate some casual relation between presence of 90 kDa isoform and age-dependent blood pressure increase because blood pressure values were quite low in the ACE 90− group and hypertension was almost absent." (PMID 22666552, 2012). "Prevalence of hypertension (46% versus 24%, respectively, p = 0.03), and left ventricular dysfunction (40% versus 14%, respectively, p = 0.01) was significantly higher in the pre-treated group in comparison to those who were not pre-treated with ACE inhibitors." (PMID 15667649, 2005). "Among patients with hypertension and albuminuria, 80% received angiotensin-converting enzyme inhibitors (ACE inhibitor) or an angiotensin receptor blocker (ARB), compared to 60% of those with albuminuria without hypertension." (PMID 40283569, 2025). "In addition to the elevated plasma levels of renin, angiotensin II, angiotensin-converting enzyme (ACE), angiotensinogen and aldosterone, renin receptors are also upregulated in patients with obesity compared with lean subjects, all of which may contribute to obesity-mediated hypertension." (PMID 40761303, 2025). "In the African American Study of Kidney Disease and Hypertension (AASK) trial, it was revealed that for Black individuals with non-diabetic renal disease, ACE inhibitors were more effective at slowing the course than other antihypertensives." (PMID 39493194, 2024). "2-3 [CQ] Are angiotensin converting enzyme (ACE) inhibitors/angiotensin II receptor blocker (ARBs) recommended for CKD patients without proteinuria and with hypertension?" (PMID 38713253, 2024). "There was no statistical difference in age, sex, hypertension, diabetes, hyperlipidemia, LBBB, mitral regurgitation and medication use (ACE inhibitors/ARBs, β-blockers, diuretics and digoxin) between LSMS and HSMS groups." (PMID 37008320, 2023). "Captopril is an angiotensin-converting enzyme (ACE) inhibitor, a pharmaceutical medication approved by the Food and Drug Administration (FDA), to treat hypertension and left ventricular dysfunction with or without myocardial infarction." (PMID 36865960, 2023). "ACE and AT1 are targets of choice for the treatment of hypertension, whereas the AT2 receptor is still not exploited due to the lack of knowledge of its physiological properties." (PMID 36768653, 2023). "In order to eliminate the influence of ACE inhibitors and ARB, the data of diabetics without hypertension and CAD was reanalyzed, and it showed that the same cut-off value of 140 mg/g still performed comparably." (PMID 35273895, 2022). "Other variables including age, gender, diabetes, dyslipidemia, hypertension, total cholesterol, HDL cholesterol, LDL cholesterol, triglycerides, aspirin, statin, beta-blockers and ACE inhibitors were not significantly correlated with plasma TF activity." (PMID 36213278, 2022).
Hypertension (continued). "Moreover, the results highlighted the idea that MVO could regulate the expression levels of targets, especially for TNF, CHRM1, ACE, IL10, PTGS2, REN, and F2, as well as neuroactive ligand–receptor interaction, the calcium signaling pathway, and PI3K-Akt signaling pathway to treat hypertension." (PMID 35308213, 2022). "Among eligible patients with hypertension and CKD, 35% were not prescribed ACE inhibitors/ARBs by providers." (PMID 34401719, 2021). "We did not have information on the specific indication of anti-HT drug use; for example, ACE-inhibitors, ATR-blockers, beta-blockers and diuretics are first line treatments also in coronary artery disease and heart failure even without hypertension." (PMID 33925829, 2021). "It was previously suggested that inhibition of ACE alone does not suffice to suppress RAAS, which provides a rationale to employ chymase inhibitors to treat hypertension." (PMID 34079459, 2021). "Patients with an RAAS-inhibitor were more likely to have hypertension and diabetes mellitus compared to patients who did not take an ARB or an ACE-inhibitor (p<0.001 and p = 0.005)." (PMID 34673795, 2021). "In this study, ACE inhibitors and β-blockers were found to have an effect on ART although the presence of hypertension was not shown to be a statistically significant factor." (PMID 33336040, 2020). "The suggestion was to prescribe an ACE-inhibitor or ARB if there was no contraindication or intolerance as these drugs are recommended by guidelines for patients with T2DM and hypertension due to their nephroprotective potential." (PMID 32903568, 2020). "The results of our study have shown that oxidative stress parameters were not significantly dependent on the ACE and AGT gene genotypes in the group of COPD-only patients and the group of patients with comorbid COPD and hypertension." (PMID 32025262, 2019). "In this study population, the statistically significant difference between participants with and without hypertension in the following RAAS sites: rs4425 and rs4337 in the ACE gene, rs29876 in the ATR gene and rs1912 in the CYP11B2 gene." (PMID 31484569, 2019). "Angiotensin-converting enzyme (ACE) inhibitors and angiotensin-receptor blockers (ARBs), which are both RAS inhibitors, are commonly used to treat hypertension, and nephrologists and cardiologists are not the only physicians prescribing RAS inhibitors." (PMID 28877239, 2017). "The results indicate that add-on treatment with an MRA in patients with hypertension and DM who do not achieve SBP<130 mm Hg with an ACE inhibitor and/or an ARB provides further benefits for BP and UACR and/or UAER." (PMID 26674759, 2016). "The subgroups of patients with newly diagnosed hypertension, aged 50–69 years, and without diabetes were found to be statistically more likely to achieve target BP when treated with AZL-M rather than an ACE-inhibitor; and the results were significant." (PMID 26956148, 2016). "In view of the recent clinical trials data, some international guidelines suggest that CCB, ACE inhibitors or ARB and not beta-blockers or diuretics should be the initial therapy in hypertension management." (PMID 21150005, 2010). "The present study shows that the weak ACE inhibitory activity of IPP and VPP in drinking water is not able to prevent the severe hypertension in this rapidly developing hypertension model, although the antihypertensive effect is evident in SHRs." (PMID 20721338, 2010). "However, a much more effective BP reduction on ACE inhibitors did not allow for a conclusion about whether this effect was specific for the ACE inhibitor therapy itself or merely reflected better control of arterial hypertension." (PMID 20441574, 2010). "In the classical system, downstream effects of ACE/AngII/AT1R are increased aldosterone synthesis and systemic hypertension as opposed to the alternative counter‐regulatory system, where downstream effects of ACE2/Ang‐ 1–7/MasR are decreased aldosterone secretion and blood pressure." (PMID 39810992, 2025).
Hypertension (continued). "The results demonstrated that angiotensin-converting enzyme (ACE) inhibitors and angiotensin II type 1 receptor antagonists (ARB) reduced IA rupture rate without altering systemic hypertension, which further suggests the activation of a regional vascular RAAS system in IA rupture." (PMID 38893035, 2024). "However, over a quarter were neither on ACE inhibitors nor ARB, even though 81.6% of the cohort had hypertension." (PMID 37833402, 2023). "Compared to non‐diabetic patients, those with DM were older, had higher blood glucose on admission, were more likely to have hypertension, negative HIV serostatus, be taking ACE inhibitors or ARBs and have a higher platelet count but lower lymphocytes, AST, and ALP." (PMID 36426913, 2023). "However, over a quarter of patients were neither on ACE inhibitors nor ARB, even though most had hypertension." (PMID 37833402, 2023). "Even though E. cava extracts (ECE) and DK show ACE inhibiting activities, no report has investigated whether ECE or dieckol is involved in the EMT of the kidney or renal fibrosis that is induced by hypertension." (PMID 33921823, 2021). "In fact, since antihypertensive drugs as ACE inhibitors can slow progression of CKD and reduce proteinuria, they could have reduced, not magnified, the impact of hypertension on TID." (PMID 32492793, 2020). "When compared with those studies, this application of PSE showed moderately attenuated hypertension in rats, which suggested that PSE might contain some other constituents rather than known compounds related to ACE inhibitors for exerting this action." (PMID 31060204, 2019). "In summary, our data suggested that the ACE-AngII-AT1R axis was hyperactive in the hypothalamus RAS of SHR where the ACE2 protein was relatively insufficient and the pituitary was not involved in the hypertension of SHR rats." (PMID 28423630, 2017). "However, similar expression of ACE, AT1R, ACE2, MasR mRNA in the pituitary of both groups of mice indicated that the pituitary RAS was not involved in the hypertension demonstrated by SHR rats." (PMID 28423630, 2017). "However, treatment with an RAS antagonist-based regimen, including an Ang II converting enzyme (ACE) inhibitor or ARB, prevented more cardiovascular events than did other regimens in diabetic patients with or without hypertension." (PMID 25884585, 2015). "Given the benefits of ACE inhibitors in SRC and the perceived decrease in incidence in SRC, some experts have advocated the use of prophylactic ACE inhibitors even in the absence of Raynaud's or hypertension." (PMID 20936135, 2010). "Users of ACE inhibitors have in average 4.5 mmHg higher SBP than non-users (i.e., users of other antihypertensive medication or individuals without pharmacological treatment of hypertension)." (PMID 16509973, 2006). "In this study, the role of angiotensin-converting enzyme (ACE) and angiotensin II (ANG II) plasma levels on disease prognosis and mortality was investigated in isolated-hypertensive (HT) patients, patients with chronic disease in addition to hypertension and COVID-19 patients without comorbidity." (PMID 34704822, 2021). "For ACE inhibitor / ARB dual therapy, benefits appear confined to symptomatic HF in patients whose symptoms persist in the presence of maximized ACE inhibitor and beta-blocker treatment and not immediately post-MI, and arguably in severe hypertension while balancing the potential adverse effects." (PMID 23866091, 2013). "However, the proportion of patients prescribed insulin, oral hypoglycaemic agents, ACE inhibitors for those with albuminuria, aspirin for those with established CVD and treatment for hypertension and hyperlipidemia (statins) at year 2 was not significantly different to baseline." (PMID 17480239, 2007).
Hypertension (continued). "Therefore, rather than blocking the ACE/Ang II/AT1R axis, activating the ACE2/Ang 1–7/MasR axis of the RAS may be more effective in improving the renal and systemic side effects of Ang II-dependent hypertension in female rats but not in male rats." (PMID 33688433, 2021).